CDC20 (cell division cycle 20)
Description:
Substrate-specific adapter and activator of the anaphase promoting complex/cyclosome (APC/C) that confers substrate specificity by binding to substrates and targeting them to the APC/C for ubiquitination and degradation. Essential for activating APC/C in the metaphase/anaphase transition of the cell cycle, targeting the degradation of cyclin B and securin. Recognizes and binds the destruction box (D box), KEB box and ABBA motifs on protein substrates. The CDC20-APC/C complex positively regulates the formation of synaptic vesicle clustering at active zone to the presynaptic membrane in postmitotic neurons (By similarity). CDC20-APC/C-induced degradation of NEUROD2 induces presynaptic differentiation (By similarity). The CDC20-APC/C complex promotes proper dilation formation and radial migration by degrading CCDC41 (By similarity). Component of the mitotic checkpoint complex (MCC), which inhibits APC/C and delays chromosome segregation until all chromosomes are properly attached to the mitotic spindle. The MCC, which consists of CDC20, MAD2L1/MAD2, BUB1B/BUBR1 and BUB3, is a key player of the spindle assembly checkpoint. The MCC-bound APC/C complex is inactive and this delays the metaphase/anaphase transition. When the spindle assembly checkpoint is silenced, the MCC-APC/C complex recruits the E2 enzyme UBCH10 and triggers the auto-ubiquitination of CDC20 in the MCC, thereby reactivating APC/C for transition into anaphase.
Synonyms: p55CDC; CDC20A; OOMD14; OZEMA14; bA276H19.3
Tractability: Small molecule: a structure with a bound ligand is known. PROTAC: it is named in the literature on targeted protein degradation; UniProt records ubiquitination sites on it; ubiquitination databases record sites on it.
Gene: Protein-coding gene on chromosome 1 (43,358,928 to 43,363,207, forward strand). Ensembl gene ENSG00000117399.
Subcellular location: Cytoplasm, cytoskeleton, microtubule organizing center, centrosome; Chromosome, centromere, kinetochore; Cytoplasm, cytoskeleton, spindle pole
Subcellular location (Human Protein Atlas): Cytosol; Nucleoplasm
Pathways (Reactome):
Cell Cycle: APC-Cdc20 mediated degradation of Nek2A; APC/C:Cdc20 mediated degradation of Cyclin B; APC/C:Cdc20 mediated degradation of Securin; APC/C:Cdc20 mediated degradation of mitotic proteins; APC/C:Cdh1 mediated degradation of Cdc20 and other APC/C:Cdh1 targeted proteins in late mitosis/early G1; Amplification of signal from unattached kinetochores via a MAD2 inhibitory signal; Cdc20:Phospho-APC/C mediated degradation of Cyclin A; Conversion from APC/C:Cdc20 to APC/C:Cdh1 in late anaphase; EML4 and NUDC in mitotic spindle formation; Inactivation of APC/C via direct inhibition of the APC/C complex; Inhibition of the proteolytic activity of APC/C required for the onset of anaphase by mitotic spindle checkpoint components; Mitotic Prometaphase; Phosphorylation of Emi1; Regulation of APC/C activators between G1/S and early anaphase; Resolution of Sister Chromatid Cohesion; SCF-beta-TrCP mediated degradation of Emi1; Separation of Sister Chromatids
Immune System: Antigen processing: Ubiquitination & Proteasome degradation
Metabolism of proteins: Ub-specific processing proteases
Signal Transduction: RHO GTPases Activate Formins
Gene Ontology:
Molecular function: anaphase-promoting complex binding; protein binding; ubiquitin-like ligase-substrate adaptor activity; ubiquitin ligase activator activity; histone deacetylase binding; ubiquitin-protein transferase activator activity
Biological process: anaphase-promoting complex-dependent catabolic process; metaphase/anaphase transition of meiosis I; positive regulation of mitotic metaphase/anaphase transition; positive regulation of ubiquitin protein ligase activity; metaphase/anaphase transition of cell cycle; mitotic spindle assembly checkpoint signaling; positive regulation of anaphase-promoting complex-dependent catabolic process; positive regulation of synapse maturation; positive regulation of synaptic plasticity; regulation of meiotic cell cycle; regulation of mitotic cell cycle; positive regulation of cell population proliferation; protein ubiquitination; regulation of dendrite development
Cellular component: anaphase-promoting complex; mitotic checkpoint complex; cytosol; kinetochore; nucleoplasm; spindle; centrosome; perinuclear region of cytoplasm; protein-containing complex; spindle pole
Genetic constraint (gnomAD): Loss-of-function variants: 31 observed, 56.26 expected, observed/expected ratio (o/e) 0.55, 90% interval 0.41 to 0.74. The synonymous counts are far from expectation, so gnomAD's model fits this gene poorly and the ratio says little. Missense variants: 451 observed, 622.11 expected, observed/expected ratio (o/e) 0.72, 90% interval 0.67 to 0.78. Synonymous variants: 185 observed, 237.36 expected, observed/expected ratio (o/e) 0.78, 90% interval 0.69 to 0.88.
Homologues: Orthologues: chimpanzee CDC20 (100% identical), macaque CDC20 (99% identical), pig CDC20 (98% identical), dog CDC20 (98% identical), guinea pig CDC20 (97% identical), rat Cdc20 (95% identical), mouse Cdc20 (95% identical), tropical clawed frog cdc20 (77% identical), zebrafish cdc20 (61% identical), Drosophila melanogaster fzy (53% identical). Paralogues in human: FZR1 (39% identical), CDC20B (34% identical).
Diseases named in the same sentence as CDC20 in open-access papers:
CDC20 is named in the same sentence as 154 diseases in open-access papers, as found by Europe PMC text mining. Sharing a sentence is not in itself a finding about the gene and the disease. The quoted sentences say what the papers report.
breast cancer (100 papers, 2010 to 2025). A primary or metastatic malignant neoplasm involving the breast. "In breast cancer (BC), CDC20 has been identified as a biomarker that has been linked to poor patient outcomes." (PMID 39061186, 2024). "In breast cancer (BC), the triple-negative breast cancer subtype, the upregulation of CDC20 is positively associated with cancer initiation, progression, metastasis, and chemotherapy resistance." (PMID 39061186, 2024). "Overexpression of Cdc20 has been observed in a variety of human tumors, including lung, gastric, and breast cancer, where its activity has been associated with tumor initiation, maintenance, and growth." (PMID 35988650, 2022). "Chromatin-associated CDC20 interactome in breast cancer cells was analyzed by using affinity purification coupled with mass spectrometry." (PMID 35954396, 2022). "The upregulation of CDC20 is associated with poor prognosis of prostate cancer, breast cancer, and colorectal cancer." (PMID 35126643, 2022). "The high mRNA expression of CDC20 was associated with a poor overall survival time in breast cancer patients." (PMID 35954396, 2022). "For instance, the high expression of the CDC20 gene were associated with poor prognosis and outcome of breast cancer patients." (PMID 33777535, 2021). "Some paper reported that CDC20 overexpression is associated with development and progression of hepatocellular carcinoma, lung adenocarcinoma, and breast cancer." (PMID 32693821, 2020). "CDC20 was highly expressed in different subtypes of breast cancer compared with normal tissues and was associated with several important clinical parameters." (PMID 32285914, 2020). "Overexpression of CDC20 is reported in various cancer including breast cancer, cervical cancer, urinary bladder cancer, and associated with poor prognosis of ovarian tumors." (PMID 31681566, 2019). "Consistent with literature on various cancers including hepatocellular Carcinoma, renal clear cell carcinoma, breast cancer, and pancreatic ductal adenocarcinoma, our study demonstrated that CDC20 is highly expressed in ACC and is associated with poor prognosis." (PMID 40688701, 2025). "This pioneering research, along with our bioinformatics analysis, would add a piece of evidence to the emerging idea that BIRC5 might contribute to breast cancer progression and drug resistance associated with CDC20 expression." (PMID 32043523, 2020). "Using Kaplan-Meier mapping instrument to access the gene chip database, we found that CDK1, PLK1, and CDC20 are associated with poor prognosis of breast cancer, which suggests that these three genes may be valuable genes." (PMID 32848800, 2020). "In the present study, we found that AME can cause S-phase arrest of breast cancer cells, downregulate the expression of CDC20, AURKB, PLK1, CCNB2, and TOP2A, and upregulate the expression of GADD45A, eventually inhibiting the proliferation of breast cancer cells." (PMID 31275405, 2019). "CDC20 has been reported to be significantly associated with poor prognosis in pancreatic, lung, bladder, colon, oral squamous cell carcinomas, and breast cancers." (PMID 30765611, 2019). "CDC20 has been reported to be significantly elevated in tumor tissues with poor differentiation and has been linked to poor prognosis in pancreatic cancer, lung cancer, bladder cancer, colon cancer, oral squamous cell carcinomas, and breast cancer." (PMID 30363964, 2018). "CDC20 (Cell Division Cycle protein 20) is associated with extremely poor outcome in breast cancer." (PMID 30038716, 2018). "Ganodermanontriol, a Ganoderma‐derived alcohol extracted from medicinal mushrooms, has been shown to decrease the level of CDC20, thereby inhibiting the growth of breast cancer cells." (PMID 40439120, 2025). "A large amount of evidence shows that CDC20 plays a carcinogenic role in human tumors and is overexpressed in many types of cancers, such as lung cancer, breast cancer, pancreatic cancer, prostate cancer, and colorectal cancer." (PMID 40650277, 2025).
breast cancer (continued). "MycoPhyto Complex, a novel mixture of medicinal mushrooms, has been found to hinder cell proliferation and induce cell cycle arrest by targeting CDC20 in breast cancer cells." (PMID 40439120, 2025). "The results from the HPA database revealed that CDC20 is highly expressed in a variety of tumors, including lung cancer, breast cancer, colorectal cancer, cervical cancer, ovarian cancer, and skin cancer." (PMID 39895786, 2025). "Another study has reported that CDC20 is frequently overexpressed in HG tumors in breast cancer and other HG tumor types." (PMID 39795587, 2024). "Another inhibitor worth mentioning is NAHA, a hydroxamic acid derivative that is reported to inhibit cell proliferation and colony formation in breast cancer cells and to reduce tumour weight in vivo by downregulating Cdc20 expression." (PMID 39595615, 2024). "Previous studies have reported that GT from G. lucidum inhibits the expression of CDC20, which controls mitotic chromosome segregation during the proliferation of human breast cancer cells." (PMID 39203053, 2024). "ERα and PR A/B protein were highly expressed in the hormone-receptor-positive breast cancer (HR+ BC) cell lines; however, cell division cycle 20 (CDC20) was only detected in the TNBC cell lines." (PMID 39000600, 2024). "CDC20, the cell division regulator, was significantly overexpressed in mammary cancer cells and indicated poor survival." (PMID 37064084, 2023). "Inhibits the expression of Cdc20 in breast cancer cells, retards cell proliferation and colony formation." (PMID 37682144, 2023). "A recent study has shown that overexpression of CDC20 promoted the metastasizing capacities of pancreatic cancer cells and breast cancer cells." (PMID 37587140, 2023). "Down-regulates Cdc20 expression and inhibits cell proliferation and invasion in breast cancer cells." (PMID 37682144, 2023). "Results from pathological analysis further suggested the overexpression of CDC20 and securin as the hallmark of triple-negative breast cancer (TNBC) with a short survival period for breast cancer patients." (PMID 35954396, 2022). "Dysregulation of the CDC20–hnRNPU axis results in diffuse chromatin and leads to drug resistance in breast cancer cells." (PMID 35954396, 2022). "Mechanistically, we found that in breast cancer CDC20-mediated hnRNPU ubiquitination regulates the formation of the CTCF–RAD21 complex, two proteins involved in the formation of chromatin loops." (PMID 35954396, 2022). "A study demonstrated that enhanced CDC20 expression in breast cancer patients was positively correlated with expression levels of YBX1." (PMID 36497125, 2022). "We showed that CDC20 interacts with hnRNPU in the chromatin fraction and regulates its ubiquitination in breast cancer cells." (PMID 35954396, 2022). "The tumor-promoting activities of CDC20 were reported in many tumors including pancreatic ductal adenocarcinoma, lung adenocarcinoma, gastric cancer, breast cancer and bladder cancer." (PMID 36494696, 2022). "In cultured cells and preclinical breast cancer models, it induced the degradation of Cdc20 to induce mitosis inhibition, thereby inhibiting cancer cell proliferation." (PMID 35680848, 2022). "The expression levels of CDC20 in breast cancer tissues are significantly higher than in normal tissues." (PMID 35954396, 2022). "Knockdown of CDC20 results in inhibition of metastatic MDA-MB-231 migration in breast cancer cell lines." (PMID 35456460, 2022). "Overexpression of CDC20 was observed in a variety of human tumors including pancreatic cancer, breast cancer, prostate cancer, lung cancer, colorectal cancer, hepatocellular carcinoma, glioblastoma, gastric cancer, and other types of human cancer." (PMID 34513754, 2021). "Cdc20 mRNA levels are elevated and are positively correlated with tumor size in breast cancer patients, suggesting its prognostic value." (PMID 33805973, 2021).
breast cancer (continued). "Cell division cycle 20 homolog (CDC20) is also studied as one of the significant regulators of the cell cycle in multiple cancer types including breast cancer, prostate cancer, and colorectal cancer." (PMID 34795689, 2021). "It is obvious that finding effective CDC20 inhibitor was very important for breast cancer targeted therapy." (PMID 34686627, 2021). "The top three proteins (CKAP5, AURKA, and CDC20) interacting with TACC3 were verified by immunoprecipitation in breast cancer cells, and CKAP5, AURKA, and CDC20 were detected in the immunoprecipitation of anti TACC3 antibody." (PMID 34149795, 2021). "Further, Cdc20 inhibition prevents breast cancer cell line migration and Cdc20 overexpression accelerates metastases of cancer cells in vitro." (PMID 33805973, 2021). "CDC20 was reported higher expressed in breast cancer and functions as an oncogene, which was also validated in our analysis." (PMID 33816496, 2021). "Meanwhile, some study confirmed that overexpression of CDC20 lead to short-term breast cancer survival again." (PMID 34686627, 2021). "Conclusion: 20 genes were regarded as hub genes of TNBC and most of them were relevant to the survival curve of breast cancer patients, especially CDC20." (PMID 34686627, 2021). "A study in the breast cancer model revealed that SMAR1 undergoes proteasomal degradation by Cdc20 in a JNK kinase–dependent manner." (PMID 33863392, 2021). "In this study, we identified 283 overlapping DEGs (105 up- and 178 down-regulated) and six hub genes (RRM2, CDC20, CCNB2, BUB1B, CDK1, CCNA2) associated with breast cancer tumorigenesis and progression based on multiple datasets." (PMID 33083112, 2020). "CDC20 was also expressed higher in breast cancer tissues compared with adjacent normal tissues of patients in our hospital, confirming the results from databases online." (PMID 32285914, 2020). "We found that CDC20 was expressed higher in different types of breast cancer, comparing with normal tissues." (PMID 32285914, 2020). "Our study reflects that CDK1, PLK1, and CDC20 are potential therapeutic targets of podophyllotoxin in breast cancer; among them, PLK1 is more worthy of further exploration." (PMID 32848800, 2020). "More in-depth experiments are needed to validate the value of CDC20 for clinical decision-making in breast cancer." (PMID 32285914, 2020). "APC/C, Cdc20, Cdh1, βTrCP, and Skp2 are several E3 ligases that have been suggested to be potential therapeutic molecules in breast cancer." (PMID 32882786, 2020). "In conclusion, the study was performed to comprehensively analyze the expression pattern, potential function, and distinct prognostic effect of CDC20 in breast cancer by pooling all currently available data online." (PMID 32285914, 2020). "Conversely, SBR grade, NPI index, HER-2 status, basal-like status, and triple-negative status were positively related to CDC20 expression in breast cancer patients with respect to normal individuals." (PMID 32285914, 2020). "Comparing with normal tissues, Oncomine database revealed that CDC20 was expressed higher in different types of breast cancer including medullary breast carcinoma, invasive ductal breast carcinoma, invasive lobular breast carcinoma, and so on." (PMID 32285914, 2020). "Breast cancer patients with lower expression of CDC20 (blue) significantly showed preferable distant metastasis-free survival." (PMID 32285914, 2020). "Oncomine analysis revealed that CDK1 and CDC20 expression were obviously elevated in most cancers, especially in breast cancer, colorectal cancer, and lung cancer." (PMID 32127012, 2020). "The co-expression profile of CDC20 was identified with a large cluster of 17779 genes across 159 breast cancer samples." (PMID 32285914, 2020). "The results indicated that patients with a more advanced stage of breast cancer tended to express higher levels CDC20." (PMID 32285914, 2020).